HNRNPA2B1 (heterogeneous nuclear ribonucleoprotein A2/B1)
Diseases named in the same sentence as HNRNPA2B1 in open-access papers (continued):
Sharing a sentence is not in itself a finding about the gene and the disease.
prostate carcinoma (continued). "Multiple studies have confirmed that HNRNPA2B1 closed related to prostate cancer progression." (PMID 34531875, 2021). "Moreover, in vitro assays demonstrated that m6A impacted the EIF3D and HNRNPA2B1 roles in proliferation and migration of prostate cancer cells." (PMID 33273988, 2020). "We presented IGF2BP3, HNRNPA2B1 and METTL14 were significantly related to RFS of prostate cancer based on mRNA expression information, while in the CNV-based regression model, YTHDF2, FTO, and ALKBH5 were notably associated with prognosis of prostate cancer." (PMID 32710725, 2020). "Here, we focused on the splicing function of HNRNPA2B1 in prostate cancer." (PMID 33273988, 2020). "Importantly, IGF2BP3, HNRNPA2B1, and METTL14 were significantly associated with RFS of prostate cancer in multivariable cox regression established on mRNA expression of m6A methylation regulators." (PMID 32710725, 2020). "Furthermore, RNA interference assays of two prognostic m6A readers EIF3D and HNRNPA2B1 were conducted to explore m6A dependence of their functions in prostate cancer cell proliferation and migration." (PMID 33273988, 2020). "Currently, there were few pieces of research related to HNRNPA2B1 an RBM15B in prostate cancer." (PMID 32710725, 2020). "Therefore, EIF3I, EIF3D, and HNRNPA2B1 can form a prognostic signature for prostate cancer relapse." (PMID 33273988, 2020). "Furthermore, we revealed the potential cancer-relevant roles of two independent prognostic factors EIF3D and HNRNPA2B1 which may represent promising biomarkers for prostate cancer." (PMID 33273988, 2020). "We analyzed HNRNPA2B1 expression in the GEO datasets (GSE3325, GSE29079, GSE94767, and GSE6919) of prostate cancer and normal prostate samples." (PMID 37215455, 2023). "In conclusion, our findings identified a novel oncogenic axis, HNRNPA2B1/miR-93-5p/FRMD6, that stimulates prostate cancer progression via an m6A-dependent manner." (PMID 37215455, 2023). "Co-immunoprecipitation identified the interaction between HNRNPA2B1 and DGCR8 in prostate cancer cells." (PMID 37215455, 2023). "HNRNPA2B1/miR-93-5p downregulated FERM domain-containing protein 6 (FRMD6), a cancer suppressor, and enhanced proliferation and metastasis in prostate cancer." (PMID 37215455, 2023). "For example, HNRNPA2B1 is negatively correlated with the immune score, stromal score, and ESTIMATE in adrenal cortical cancer, as well as Th1 and Th17 in prostate cancer." (PMID 36189296, 2022). "Some researchers analyzed the important m6A RNA regulators, which act as prognosis factors in prostate cancer, and identified RBMX, NXF1, YTHDF1, HNRNPA2B1, and TRMT112 as critical genes that have great effects on the prognosis of PCa patients." (PMID 34899855, 2021). "In univariate Kaplan-Meir analyses, high expression of HNRNPA2B1 and low expression level of FTO had poorer RFS of prostate cancer." (PMID 32710725, 2020). "To confirm our funding, we added critical clinical characteristics such as diagnosed age, GS, tumor T stage and N stage, the three m6A methylation regulators (IGF2BP3, HNRNPA2B1, and METTL14) were still remarkably related with prognosis of prostate cancer." (PMID 32710725, 2020). "In this study, we found HNRNPA2B1, METTL3, and RBM15B were overexpressed not only in tumor samples but also in high GS prostate cancer patients." (PMID 32710725, 2020). "Here, we found that HNRNPA2B1 and FRMD6 were negatively correlated in prostate cancer." (PMID 37215455, 2023). "The translation initiation factor subunit EIF3D may delay the prostate cancer progression while the splicing factor HNRNPA2B1 may promote prostate cancer progression, in vitro assays proved the roles of EIF3D as well as HNRNPA2B1 in prostate cancer cells." (PMID 34899855, 2021). "Similarly, IGF2BP3 (p < 0.05), HNRNPA2B1 (p < 0.05) and WTAP (p < 0.05) were significantly related to prostate cancer RFS in univariate cox regression analyses." (PMID 32710725, 2020).
prostate carcinoma (continued). "Consistent with results based on prostate cancer patients from TCGA, we also found that HNRNPA2B1 was not only highly expressed in patients with high GS, but also significantly associated with unfavorable RFS (HR = 2.3e+10, 95%CI 3.9e+3 - 1.4e+17)." (PMID 32710725, 2020). "However, as far as we know, a role of HNRNPA2B1 as an m6A reader has not yet been reported in prostate cancer." (PMID 37215455, 2023). "The role of HNRNPA2B1, METTL3, and RBM15B may play an oncogene in prostate cancer." (PMID 32710725, 2020).
non-small cell lung carcinoma (12 papers, 2019 to 2025). A group of at least three distinct histological types of lung cancer, including non-small cell squamous cell carcinoma, adenocarcinoma, and large cell carcinoma. "HNRNPA2B1 was initially discovered as a tumor-associated antigen in non-small cell lung cancer." (PMID 40703632, 2025). "Long non-coding RNA (lncRNA) CACNA1G-AS1 promotes the expression of hnRNPA2B1 in non-small cell lung cancer (NSCLC) cell lines, inducing malignant cell invasion, migration, and epithelial-mesenchymal transformation (EMT)." (PMID 33505405, 2020). "Overexpression of hnRNPA2B1 is well-established as a biomarker for the early stages of non-small cell lung cancers, epithelial transformation, and carcinogenesis." (PMID 30755586, 2019). "Patients with non-small cell lung cancer who are positive for HNRNPA2B1 have a worse prognosis." (PMID 40703632, 2025). "CACNA1G-AS1 exerts its malignant function by HNRNPA2B1 in non-small-cell lung cancer." (PMID 34238292, 2021). "LINC01234 interacts with HNRNPA2B1, leading to the recruitment of DGCR8 and promoting the processing and maturation of miR-106b-5p, which inhibits CRY2 and promotes the growth of non-small cell lung cancer (NSCLC) cells." (PMID 37151887, 2023).
bladder cancer (10 papers, 2020 to 2024). "It was found in humans and animal models that METTL3, FTO, IGF2BP1, IGF2BP3, YTHDF1, YTHDF 2, ELAV-like protein 1 (ELAVL1), HNRNPA2B1 were upregulated in bladder cancer cells." (PMID 37701836, 2023). "We then evaluated the relationship between HNRNPA2B1 expression and immune infiltration of bladder cancer, and found that HNRNPA2B1 expression was positively correlated with the infiltration of CD8 + T cells, neutrophils and dendritic cells." (PMID 37072750, 2023). "For instance, lncRNA LNMAT2 can be imported into bladder cancer exosomes through hnRNPA2B1 and internalized by human lymphatic endothelial cells, ultimately leading to lymphangiogenesis and lymphatic metastasis." (PMID 37735657, 2023). "Of note, two identified treatment outcome-related genes, FMR1 and HNRNPA2B1, are found in the turquoise module, indicating the important role of these two m6A regulators in the immunotherapy of bladder cancer." (PMID 36189296, 2022). "In the context of bladder cancer progression, exosomes from bladder cancer cells contain a long non-coding RNA, lymph node metastasis-associated transcript 2 (LNMAT2), loaded through interaction with heterogeneous ribonucleoprotein A2B1 (hnRNPA2B1)." (PMID 38528957, 2024). "In the TCGA cohort of bladder cancer patients, the expression of SBF2-AS1 and HNRNPA2B1 is significantly correlated with the prognosis, and may be an independent prognostic factor in patients with Bladder cancer." (PMID 37072750, 2023). "We infer that SBF2-AS1 regulates HNRNPA2B1 transcription and related signal pathways through has-miR-582-5p may affect the occurrence and development of bladder cancer and immune escape." (PMID 37072750, 2023). "Further mechanistic studies uncovered that LNMAT2 could be encapsulated into exosomes secreted by bladder cancer cells through direct interaction with hnRNPA2B1 (heterogeneous nuclear ribonucleoprotein A2B1)." (PMID 33520725, 2020). "However, we found that expression of FMR1 and HNRNPA2B1 were not correlated with the overall survival in bladder cancer patients based on TCGA-BLCA dataset, who were not treated with immunotherapy." (PMID 36189296, 2022).
osteosarcoma (10 papers, 2021 to 2026). A usually aggressive malignant bone-forming mesenchymal neoplasm, predominantly affecting adolescents and young adults. "Among them, HNRNPA2B1 was suggested to be an independent prognostic risk factor in patients with osteosarcoma and predict poor survival rates." (PMID 34094986, 2021). "Importantly, to validate the biological function of m6A regulators in sarcoma, we performed loss of function experiments for two regulators, YTHDF2 and HNRNPA2B1 in osteosarcoma cell line." (PMID 35847857, 2022). "Thus, methionine restriction can decrease RNA m6A modification as well as the expression of HNRNPA2B1, both of which can cause the reduction of C1orf112 protein expression and eventually alter the proliferation and metastatic phenotype of osteosarcoma (and potentially other sarcoma) cells." (PMID 38769167, 2024). "Furthermore, m6A-related regulatory factors were abnormally expressed in osteosarcoma, and HNRNPA2B1 may be an independent risk factor for OS." (PMID 36157883, 2022). "Interestingly, three proteins, KHDRBS1, FUBP1, and HNRNPA2B1, are involved in either RNA processing or RNA modification, highlighting the potential role of RNA regulation in osteosarcoma pathogenesis." (PMID 37681913, 2023). "Based on two large-scale cohorts, HNRNPA2B1, HNRNPC, RBM15, YTHDF1, and YTHDC1 expression levels are upregulated in osteosarcoma tissues." (PMID 34094986, 2021).
cervical cancer (9 papers, 2020 to 2024). A primary or metastatic malignant neoplasm involving the cervix. "The expression of RBM15 and HNRNPA2B1 in our study showed significant differences between cervical cancer and normal samples." (PMID 35572541, 2022). "One study demonstrated that down-regulation of HNRNPA2B1 can inhibit the cell proliferation, tumor invasion, and cell cycle progression through the PI3K/AKT signaling pathway of cervical cancer cells, thus triggering cell apoptosis." (PMID 36401285, 2022). "We speculated that low expressed TRPV1 promotes cervical cancer tumorigenesis through YTHDF1/2/3, HNRNPA2B1, YTHDC1/2, ZC3H13, and METTL14 modification." (PMID 36072430, 2022).
endometriosis (9 papers, 2020 to 2025). The growth of functional endometrial tissue in anatomic sites outside the uterine body. "Down-regulated METTL3, heterogeneous nuclear ribonucleoprotein C (HNRNPC), and A2/B1 (HNRNPA2B1) have been linked to the development of endometriosis." (PMID 37891533, 2023). "Abnormalities in the gene transcription factors network associated with endometriosis might affect the expression of HNRNPA2B1 and HNRNPC." (PMID 33232273, 2020). "Until now, the role of HNRNPC in endometriosis remained unclear, while the protein levels of HNRNPA2B1 were revealed to be downregulated in endometriosis." (PMID 36672827, 2022). "The lower expression levels of HNRNPA2B1 are correlated with higher levels of Th17 cells and neutrophil infiltration, which have been proved to be increased in endometriosis." (PMID 36672827, 2022). "Both HNRNPA2B1 and HNRNPC were associated with the severity of endometriosis in eutopic samples, and also exhibited diagnostic potential for endometriosis." (PMID 33232273, 2020). "Another study showed the abnormal expression of m6A regulators in endometriosis and indicated that hnRNPA2B1 and hnRNPC might be correlated with immune response, serving as useful diagnostic biomarkers for endometriosis." (PMID 36632456, 2023). "Furthermore, HNRNPA2B1 and HNRNPC that are m6A RNA-binding proteins were demonstrated to serve as useful diagnostic biomarkers for endometriosis." (PMID 35755020, 2022). "It is likely that these changes in the expression of HNRNPA2B1 and HNRNPC are associated with the abnormal immune response and that these factors may serve as efficient m6A-related diagnostic biomarkers in endometriosis." (PMID 33232273, 2020). "In conclusion, we observed significant dysregulation of m6A regulators in endometriosis, and found that HNRNPA2B1 and HNRNPC might correlate with the immune response and serve as useful diagnostic biomarkers for endometriosis." (PMID 33232273, 2020). "Both HNRNPA2B1 and HSPC159 have previously been linked with epithelial–mesenchymal transition (EMT) in cancer; EMT is thought to drive malignant invasion and metastasis and has also been proposed to contribute, in part, to the detachment and dissemination of endometrial cells in endometriosis." (PMID 33317189, 2020). "HNRNPA2B1 and HNRNPC are involved in the regulation of immune responses, and their abnormal expression is closely related to the pathogenesis of endometriosis." (PMID 40356909, 2025). "Though the expression of HNRNPA2B1 and FTO showed opposite trends between bioinformatic analysis and validation, they demonstrated a significant expression change in the endometriosis group at the protein level." (PMID 36672827, 2022). "Three m6A regulators (HNRNPC, HNRNPA2B1, and FTO) were identified as being significantly overexpressed in endometriosis patients and were visualized utilizing a boxplot." (PMID 36672827, 2022). "Many studies have shown that the pathogenesis of endometriosis may be related to m6A, and some of these regulators, including METTL3, YTHDF2, YTHDF3, HNRNPC, HNRNPA2B1, and FTO, are significantly dysregulated in the ectopic endometrium." (PMID 40356909, 2025). "Another study has also identified three different m6A regulators (FTO, HNRNPC, and HNRNPA2B1) between the endometriosis and non-endometriosis groups." (PMID 37891533, 2023). "For example, the first investigation into how m6A regulators function in endometriosis indicated that m6A regulators in endometriosis, such as METTL3, YTHDF2, YTHDF3, HNRNPC, HNRNPA2B1, and FTO, are significantly dysregulated compared with normal endometrial tissue." (PMID 36894952, 2023). "HNRNPA2B1 and HNRNPC may influence immune pathways and the infiltration of immune cells in endometriosis." (PMID 33232273, 2020).
viral infection (9 papers, 2020 to 2026). "Heterogeneous nuclear ribonucleoprotein A2/B1 (hnRNP A2/B1) is a multifunctional nucleic acid metabolism regulator with established roles in viral infection and tumorigenesis." (PMID 41888191, 2026). "The roles of hnRNPA2B1 in virus infection are complex, as it exerts pro-inflammatory, anti-inflammatory, or pathopoiesis effects through interactions with multiple DNAs, RNAs, and proteins." (PMID 39166862, 2024). "Herein, we show that PAC5 is the first small-molecule agonist of hnRNPA2B1 for the inhibition of viral infection." (PMID 36726760, 2023). "In summary, our study suggested hnRNPA2B1 a druggable target with broad-relevance to virus infection." (PMID 36726760, 2023). "During viral infection, HNRNPA2B1 functions as a reader protein that detects viral DNA and induces m6A modification to initiate an innate immune response." (PMID 37139237, 2023). "Recently, hnRNPA2B1 has been suggested as an attractive regulatory protein for viral infection." (PMID 36726760, 2023). "hnRNPA2B1 mRNA levels are constitutively expressed during viral infection." (PMID 33505405, 2020). "Furthermore, our ABPPs study indicated that the principal target of PAC5 is hnRNPA2B1, a previously unknown drug target for viral infection." (PMID 36726760, 2023). "Our data revealed that PAC5, a highly selective and potent agonist of hnRNPA2B1, initiates the TBK1-IRF3 pathway leading to upregulation of type I IFNs, phosphorylation of STAT1/2, and inhibition of viral infection in vivo and in vitro." (PMID 36726760, 2023). "Reportedly, agonists of HNRNPA2B1 dramatically ameliorated lung damage induced by SARS-CoV-2 Omicron (BA.1) infection in a hamster model and significantly suppressed viral infection." (PMID 38025778, 2023).
Alzheimer disease (8 papers, 2013 to 2025). A progressive, neurodegenerative disease characterized by loss of function and death of nerve cells in several areas of the brain leading to loss of cognitive function such as memory and language. "Also, we recently found that hnRNPA2B1 is essential for neuronal wellbeing in Alzheimer's disease, compatible with the stress-associated changes in AS." (PMID 23717260, 2013). "Of note, reduced levels of hnRNPA1 and hnRNPA2B1 have been reported in cases of Alzheimer’s disease, suggesting a connection between RBP homeostasis and neuronal health in multiple disorders." (PMID 30937520, 2019).
Obesity (8 papers, 2022 to 2026). Accumulation of substantial excess body fat. "Consistent with this, mice haploinsufficient for Hnrnpa2b1 (A2B1 HET) are protected from high-fat-diet-induced obesity and display reduced M1 macrophage infiltration in eWAT." (PMID 41596407, 2026). "In parallel with its thermogenic role, hnRNPA2B1 contributes to adipose tissue inflammation, particularly in diet-induced obesity." (PMID 41596407, 2026). "Similar to RBM15, HNRNPC, and HNRNPA2B1, MYC expression level significance was also negatively related to obesity." (PMID 36120320, 2022).
pancreatic ductal adenocarcinoma (8 papers, 2016 to 2023). An infiltrating adenocarcinoma that arises from the epithelial cells of the pancreas. "HnRNPA2B1 interacted and regulated oncogenic KRAS signaling in pancreatic ductal adenocarcinoma cells." (PMID 35875075, 2022). "Knockdown of HNRNPA2B1 using small hairpin RNAs impaired tumor viability and proliferation via inactivating c-Akt signaling pathway in KRAS phosphorylation-dependent pancreatic ductal adenocarcinoma cells." (PMID 32710725, 2020). "Previously, hnRNPA2B1 was reported to interact directly with KRAS proteins as a partner without regulating KRAS expression in pancreatic ductal adenocarcinoma (PDAC)." (PMID 37716979, 2023). "In addition, hnRNPA2B1 can interact with phosphorylated KRAS protein, functioning as a regulator of KRAS-dependent tumorigenesis through the critical pancreatic ductal adenocarcinoma signaling pathway PI3K/AKT." (PMID 34044823, 2021). "HnRNPA2B1 could act as a novel regulator of oncogenic K-ras, modulating PI3K/AKT/mTOR signal pathway in K-ras-dependent pancreatic ductal adenocarcinoma cells." (PMID 26805816, 2016).
tauopathy (7 papers, 2022 to 2025). Neurodegenerative disorders involving deposition of abnormal tau protein isoforms (tau proteins) in neurons and glial cells in the brain. "Previously we showed that interaction of MAPT with HNRNPA2B1 and m6A RNA mediates the progression of tauopathy." (PMID 37292629, 2023).
dementia (6 papers, 2020 to 2025). Loss of intellectual abilities interfering with an individual's social and occupational functions. "However, the patient with the hnRNPA2B1 variant had progressive cognitive impairment/dementia but was determined to have a PLS phenotype." (PMID 36515702, 2023). "The KEGG and GO analyses further support the correlations of Rbm15b and Hnrnpa2b1 with post-synaptic modulation in the development of AD related dementias." (PMID 40666518, 2025). "One family with myopathy, Paget’s disease of bone, dementia and ALS was described with a mutation in the heterogeneous nuclear ribonucleoprotein A2/B1 (HNRNPA2B1) which encodes HNRNPA2 and HNRNPB1 proteins that play a role in the packaging of nascent mRNA, thus, in several mRNA-related processes." (PMID 36399165, 2023).
lung squamous cell carcinoma (6 papers, 2021 to 2022). "Knockdown of HNRNPA2B1 pronouncedly reduced the migration and invasion of lung squamous cell carcinoma cell line DLKP-M." (PMID 36536402, 2022). "With the analysis with clinical data from the TCGA and CPTAC database, we found that hnRNPA2B1 was significantly upregulated in both lung adenocarcinoma (LUAD) and lung squamous cell carcinoma (LUSC) patients at mRNA levels." (PMID 34884671, 2021). "Next, we found that HNRNPA2B1 was associated with diffuse large B-cell lymphoma (DBLC) and lung squamous cell carcinoma (LUSC), but not ACC, as shown in the radar plot." (PMID 33746977, 2021).